XKR5 (XK related 5)
Synonyms: HARL2754; UNQ2754; XRG5A; XRG5BM
Tractability: Antibody: UniProt places it where antibodies can reach, with medium confidence; UniProt predicts a signal peptide or a membrane-spanning region; its Gene Ontology location is reachable by antibodies, with medium confidence.
Gene: Protein-coding gene on chromosome 8 (6,805,013 to 6,835,526, reverse strand). Ensembl gene ENSG00000275591.
Subcellular location: Cell membrane
Gene Ontology:
Cellular component: membrane; plasma membrane
Genetic constraint (gnomAD): Loss-of-function variants: 46 observed, 34.78 expected, observed/expected ratio (o/e) 1.32, 90% interval 1.04 to 1.69. The synonymous counts are far from expectation, so gnomAD's model fits this gene poorly and the ratio says little. Missense variants: 1,169 observed, 812.31 expected, observed/expected ratio (o/e) 1.44, 90% interval 1.37 to 1.51. Synonymous variants: 466 observed, 343.89 expected, observed/expected ratio (o/e) 1.36, 90% interval 1.25 to 1.46.
Homologues: Orthologues: chimpanzee XKR5 (97% identical), macaque XKR5 (93% identical), pig XKR5 (67% identical), rabbit XKR5 (66% identical), mouse Xkr5 (65% identical), dog XKR5 (59% identical), rat Xkr5 (55% identical), tropical clawed frog xkr5 (36% identical), zebrafish xkr5b (28% identical), zebrafish xkr5a (23% identical). Paralogues in human: XKR6 (18% identical), XKR7 (18% identical), XKR4 (16% identical), XKR8 (13% identical), XKR9 (10% identical).
Diseases named in the same sentence as XKR5 in open-access papers:
XKR5 is named in the same sentence as 1 disease in open-access papers, as found by Europe PMC text mining. Sharing a sentence is not in itself a finding about the gene and the disease.
XKR5 shares sentences with these, for which no sentence is quoted: mastocytoma (1 paper).